CRP (C-reactive protein)
Diseases named in the same sentence as CRP in open-access papers (continued):
Sharing a sentence is not in itself a finding about the gene and the disease.
diabetes (continued). "For example, the authors found that increased serum levels of the C-reactive protein/albumin rate have been associated with renal damage in diabetics with nephropathy in the CARE TIME study." (PMID 37370958, 2023). "We observed that those in the lowest wealth tertile with elevated CRP were at increased risk of developing CHD, stroke, and diabetes/high blood glucose over 14 years of follow-up compared to those in the highest wealth tertile with low CRP." (PMID 37808231, 2023). "The administration of phytosterols in a diet has been proven to lower the risk of multiple cancer risk factors, including obesity, diabetes, hypertension, and serum CRP levels." (PMID 37111115, 2023). "Among all patients, liver MRI abnormalities were associated with obesity, diabetes, higher Charlson Comorbidity Index, acute CRP of more than 5 mg/L, and acute steroid treatment." (PMID 37748493, 2023). "Based on previous studies from the literature, elevated CRP levels have been associated with cardiovascular mortality in adults as well as with an increased risk of diabetes and insulin resistance in adults, adolescents, and children." (PMID 38189043, 2023). "Inflammation plays a critical role in the development of diabetes, and higher CRP level is a risk factor for developing DM." (PMID 37790129, 2023). "The elevated levels of CRP are linked to increased HbA1c and are a risk factor for the development of diabetes and insulin resistance." (PMID 37022674, 2023). "A large nationally population-based study has suggested that social isolation increase the risk of inflammation (C-reactive protein, CRP), and the effect of social isolation on hypertension exceeded that of clinical risk factors such as diabetes in old age." (PMID 37032930, 2023). "Here, it was found that the presence of hypertension and diabetes, as well as the levels of TC, CRP, and SAA, were significantly associated with CHD." (PMID 37441706, 2023). "The presence of NOAF was found to be associated with several factors, including age, diabetes mellitus, hypertension, LA diameter, NT-proBNP levels, CRP levels, sST2 levels, Killip class of ≥2, and a final TIMI flow grade of <3." (PMID 37808879, 2023). "Eight risk factors (1 kg higher body weight, diabetes, education, hypertension, hypercholesterolemia, pre-operative C-reactive protein (CRP), pre-operative interleukin 6, pre-operative S100b) were detected in a mix of surgery types." (PMID 36836145, 2023). "CRP was associated with five KP metabolites, BMI with two, and smoking and diabetes with one of the metabolites." (PMID 36986451, 2023). "Age, family history of diabetes, systolic blood pressure, and biochemical markers including C-reactive protein and triglycerides were significantly associated with higher glycated hemoglobin levels." (PMID 37777593, 2023). "CRP has also been associated with the inflammation of comorbidities such as cardiovascular disease, diabetes, metabolic syndrome, pulmonary diseases, and depression." (PMID 35344152, 2023). "Elevated CRP levels have been previously associated with diseases including diabetes and cardiovascular disease and were found in African Americans and Black ethnic groups at higher concentrations." (PMID 36963080, 2023). "The risk factors such as hospitalization in the ICU, age, diabetes, and biomarkers such as CRP, PO2, WBC, NLR, AST, BUN, and respiratory distress had a significant relationship with LOHS." (PMID 37415112, 2023). "Elevated serum C-reactive protein (CRP) levels were associated with a fourfold increase in risk for future diabetes, according to data collected in women’s health research." (PMID 38132485, 2023). "Common aging-related disease levels including cardiovascular disease, hypertension, and diabetes are associated with elevated CRP, all of which are risk factors for NAFLD." (PMID 37893085, 2023).
diabetes (continued). "Examined risk factors included blood pressure, smoking, diabetes, lipids, adiposity, history of stroke or myocardial infarction (MI), socioeconomic status, kidney function, C-reactive protein, and alcohol consumption." (PMID 37851596, 2023). "High-sensitivity C-reactive protein (hs-CRP) is a systemic inflammatory marker associated with the progression of diabetic nephropathy in patients with type 2 diabetes mellitus." (PMID 37370958, 2023). "Participants in the moderate to severe malnutrition risk group of GNRI (GNRI < 92) had higher lymphocytes, C-reactive protein levels, higher prevalence of diabetes, and chronic kidney disease." (PMID 37465450, 2023). "We did not detect a significant association of Nrf2 protein with the presence of diabetes, proteinuria, and C-reactive protein." (PMID 37107307, 2023). "The stated factors also cause an increase in the inflammatory marker C Reactive Protein (CRP), which further increases the risk of peripheral vascular disease and diabetes." (PMID 37108307, 2023). "There are a number of cardiovascular diseases and several cardiometabolic risk factors that have been reported to be associated with lower risk of diabetes in larger individuals, including blood pressure, triacylglycerols, CRP levels, and adiponectin." (PMID 36983200, 2023). "In the RELAX trial, the presence of an increased number of comorbidities such as obesity, diabetes, anaemia and chronic kidney disease in HFpEF patients was associated with higher C-reactive protein (CRP) levels." (PMID 37456816, 2023). "Although some studies have suggested that sex differences exist in risk factors for PAD, such as smoking, hypertension, diabetes, and C-reactive protein (CRP), the extent of these differences remains to be reliably quantified." (PMID 37851596, 2023). "We found a marked association between high hs-CRP and future diabetes incidence at 7-year follow-up in this study of adults from a general Norwegian population." (PMID 37775289, 2023). "Black respondents were significantly more likely to report diabetes-related kidney issues than White respondents and appeared to have significantly greater C-reactive protein levels and diabetes risk based on HbA1C than White or Hispanic/Latino respondents." (PMID 35403576, 2022). "In the main study, both RA and CRP ≥ 3 mg/L were significantly associated with all-cause mortality in the Step1 models and the Step2 models (additionally adjusted for body mass index, diabetes, hypertension, smoking and total cholesterol)." (PMID 36329101, 2022). "CRP as a risk factor for the 6-year development of diabetes mellitus and the metabolic syndrome were evaluated in the Mexico City Diabetes Study." (PMID 36304737, 2022). "Older age, male gender, history of diabetes and hypertension, and elevated C-reactive protein (CRP) and lactate dehydrogenase (LDH) levels were associated with a significantly increased risk of developing cytokine release syndrome (CRS)." (PMID 35989853, 2022). "They examined the relationship between four risk factors (depression, exercise, C reactive protein, and diabetes) and coronary heart disease, using various study designs." (PMID 35560730, 2022). "Since diabetes is also associated with atherosclerosis and chronic inflammation, we strive to find out the relationship associated between Hs-CRP levels and diabetes." (PMID 36381804, 2022). "HbA1C is, in addition to its role in diabetes diagnosis, a marker of metabolically unhealthy biological ageing, and CRP reflects chronic inflammation linked to biological ageing." (PMID 34935094, 2022). "After further adjustment for potential confounders, including hemoglobin concentration, C-reactive protein, cardiovascular disease, and diabetes, the association remained materially unchanged (model 2 OR (95% CI): 0.6 (0.4; 0.9); p = 0.03)." (PMID 35889768, 2022).
diabetes (continued). "Except for age, male gender, lower BMI, diabetes, longer dialysis duration, malnutrition (such as lower serum albumin/pre-albumin), and high-sensitive C-reactive protein (Hs-CRP) were found associated with sarcopenia also in a multivariate logistic regression." (PMID 36458164, 2022). "Patients with raised basal levels of CRP are at an increased risk of cardiovascular disease, type 2 diabetes mellitus, and systemic hypertension." (PMID 36381804, 2022). "Despite that lymphopenia, elevated CRP, diabetes, and hypertension were all significant risk factors for prolonged hospitalization, however, none of them raised the hazard risk for mortality." (PMID 36494866, 2022). "CRP had been found to have complex interactions between several risk factors in elderly individuals, including smoking, diabetes, hypertension, BMI, and lipid metabolism." (PMID 36338499, 2022). "We found a significant positive association of elevated level of C-reactive protein with type 2 diabetes mellitus." (PMID 35300754, 2022). "After further adjustment for potential confounders, including hemoglobin concentration, C-reactive protein, cardiovascular disease, and diabetes, the association remained materially unchanged (model 2 OR (95% CI): 0.3 (0.1; 0.7); p = 0.01)." (PMID 35889768, 2022). "The results also showed that age, diabetes, overweight/obesity, hypertension, hyperuricemia, hypertriglyceridemia, remnant cholesterol, and CRP were independent risk factors for CKD." (PMID 36374233, 2022). "Previous epidemiologic studies reported that hyperglycemia, diabetes status, and higher CRP levels were independently associated with the incidence of dementia." (PMID 35252292, 2022). "In the subgroup analysis, 6–12-month hs-CRP levels, diabetes mellitus (DM), and age ≥60(years)were associated with a higher risk of ISR." (PMID 36005411, 2022). "In univariate models, higher C-reactive protein, lactate dehydrogenase, D-dimer, neutrophil-lymphocyte ratio, diabetes mellitus, and bilateral infiltrate on chest x-ray were associated with greater odds of requiring intubation." (PMID 35274051, 2022). "The cause of the increased CRP is thought to be the presence of H+ and the development of arteriolitis owing to vascular narrowing in hyperlipidemia, obesity, diabetes, and heavy drinking." (PMID 35965526, 2022). "Excessive sugar-sweetened beverages (SSB) consumption and abdominal obesity have been independently linked to numerous disorders, including diabetes and elevated C-reactive protein (CRP)." (PMID 36613000, 2022). "The population-based cohort and meta-analysis studies showed that inactivity or obesity stimulates hepatic secretion of CRP, which increases the risk of diabetes." (PMID 36434695, 2022). "Hypertension, diabetes, and elevated hi-CRP were independent risk factors for ICAS, while overweight and obesity appeared to have a protective effect against vascular damage." (PMID 35047049, 2022). "The glycA NMR signal has been shown to be a predictor of cardiovascular disease and diabetes mellitus, independently of the increase in CRP, associated with these conditions." (PMID 35413834, 2022). "It is reported that CRP significantly increased in the presence of inflammation and the elevated CRP level was associated with insulin resistance and an increased risk of diabetes." (PMID 36463101, 2022). "In this study, aging, overweight, hypertension, diabetes and smoking seemed to be associated with high CRP levels." (PMID 35707008, 2022). "In linear regression adjusted to diabetes mellitus, neurological disease, and CRP level with the length of stay, only CRP was associated with increased hospital stay (p = 0.42, p = 0.64, and p = 0.003 respectively)." (PMID 36555921, 2022). "The association of diabetes mellitus, serum creatinine, albumin, CRP, GNRI, and CI levels with CV mortality continued in age and sex-adjusted multivariate models (Table-2)." (PMID 36326327, 2022).
diabetes (continued). "In another multicentric study (CAPIRE) (including patients with coronary calcium), HRP were associated with male sex, older age, diabetes and biomarkers of inflammation such as c-reactive protein and PTX-3." (PMID 36140444, 2022). "Previous studies have shown that CRP can be a prognosis, and diagnostic markers for cardiovascular disease and diabetes have been established as appropriate reference domains for CRP to identify disease severity and disease risk classification." (PMID 35178206, 2022). "Meanwhile, it is shown that higher hot tea consumption had an inverse association with C-reactive protein, which was reported to be an indication of a series of metabolic disorders (i.e., hypertension, diabetes, hyperlipidemia, etc.)." (PMID 36079760, 2022). "For example, a prospective study of a general Japanese population showed that an elevated hs-CRP level is an independent predictor of diabetes after adjustment for comprehensive risk factors." (PMID 35740093, 2022). "Our findings demonstrated that salivary CRP and insulin were associated with hyperglycemia, obesity, and possibly diabetes in adolescents." (PMID 35757631, 2022). "Since the incidence of T2DM is expected to increase in the following years dramatically, further analysis of the CRP and diabetes association is needed to provide an adjunctive method for early detection of risk for this disease." (PMID 35620114, 2022). "Female gender, diabetes mellitus, hypertension, and ischemic heart disease were associated with higher levels of both the first and second CRP measurements in our cohort." (PMID 35683538, 2022). "Cardiovascular diseases, diabetes mellitus, anxio-depressive symptoms, asthma, arthritis and high levels of hs-CRP conferred a greater risk for OSA." (PMID 35332170, 2022). "Associations between venular tortuosity and cardiometabolic risk factors differed according to diabetes status (p interaction <0.01) for total fat mass index, HbA1c, C-reactive protein, white cell count and granulocyte count." (PMID 35852586, 2022). "The results indicated that age, diabetes mellitus (DM), overweight/obesity, hypertension, hyperuricemia, hypertriglyceridemia, remnant cholesterol (RC), and C-reactive protein (CRP) were independently associated with a higher CKD prevalence." (PMID 36374233, 2022). "The findings in our study support previous evidence that CRP affects blood glucose levels and BMIz that can increase the risk of diabetes." (PMID 35757631, 2022). "In patients hospitalised with CoVID-19, high initial C-reactive protein was independently associated with the need for intubation and, in conjunction with high lactate dehydrogenase and diabetes mellitus, was strongly predictive of intubation." (PMID 35274051, 2022). "CRP is a diabetes marker, and its combination with obesity is positively associated with a higher risk of diabetes." (PMID 36618686, 2022). "For instance, polymorphisms of CRP 3872 G-T G at rs1205 were associated with elevated CRP level associated with diabetes mellitus type 2 (DM2), cardiovascular diseases (CVD), and all the group of neuropathies related to metabolic disorders." (PMID 36428884, 2022). "At the same time, changes in CRP levels are closely associated with cardiovascular disease risk factors such as diabetes, hypertension, and hyperlipidemia." (PMID 36406928, 2022). "Like other cytokines, CRP is associated with cardiovascular disease and diabetes and is one of the factors of chronic inflammatory response in the human body." (PMID 36012088, 2022). "Previous work has observed higher levels of loneliness and CRP among Black vs. White older adults, and there are well-established health disparities among Black individuals in diseases linked with CRP (e.g., heart disease, stroke, and diabetes)." (PMID 35087386, 2021).
diabetes (continued). "There is evidence that women have higher levels of CRP than men and that CRP is a prototypic marker of inflammation and is an important risk factor for diabetes, hypertension, atherosclerosis, and coronary heart disease." (PMID 33494231, 2021). "After adjusting for single risk factors in the overall group, for BMI, hypertension, diabetes, hs-CRP, HDL and smoking a reduction of effect strength was observed." (PMID 34588554, 2021). "The low IL-37, diabetes mellitus, high CRP, NT-pro BNP, and hs-cTnI were independent risk factors affecting poor prognosis of patients with ACS." (PMID 34580597, 2021). "IL-6R rs4537545*T allele has been associated with increased circulating CRP levels, a decreased risk of RA in mixed ancestries, while an increased risk of diabetes and asthma from the UK Biobank Neale’s lab rapid GWAS (See Web Resources)." (PMID 33517400, 2021). "Hypertension, diabetes, high serum UA and hs-CRP were independent risk factors related to mortality in CAPD patients." (PMID 34532198, 2021). "We conclude that high sensitivity C-reactive protein can be used as an early predictor of inflammation in pre-diabetes and can be a marker of underlying deranged sugar levels and lipid profile in pre-diabetics unaware of their health status." (PMID 34868746, 2021). "PhenoAgeAccel also was genetically more correlated than BioAgeAccel with creatinine, cystatin C, HbA1c, and CRP – biomarkers linked to kidney function, diabetes, and inflammation." (PMID 34038024, 2021). "GDF15 levels were strongly correlated with age and positively correlated with cardiovascular risk factors (hypertension and diabetes) and inflammation (C-reactive protein: CRP > 3 mg/L)." (PMID 34445593, 2021). "In multivariable analyses, elevated CRP level (≥ 10.0 mg/L) was significantly associated with QTc length, and diabetes and use of any QTc prolonging medications were significantly associated with QTc ≥ 440 ms." (PMID 34715924, 2021). "Logistic regression revealed that low IL-37, diabetes, high CRP, NT-pro BNP, and hs-cTnI in the blood were independent risk factors for poor prognosis in patients with ACS." (PMID 34580597, 2021). "After adjustment for gender, age, smoking history, drinking history, history of dyslipidemia, history of diabetes, lipid levels, and blood glucose levels, CRP levels were significantly associated with patient outcomes." (PMID 34212039, 2021). "A higher intake of total and insoluble dietary fiber has been found to reduce the risk of diabetes by lowering the levels of inflammatory markers (such as fibrinogen activator inhibitor-1, resistin, C-reactive protein, and interleukin-6)." (PMID 34276373, 2021). "Many studies were consistent with the reverse relationship between LTPA and risk factors of CVD, such as hypertension, diabetes, obesity, and C-reactive protein." (PMID 34124188, 2021). "Seven variables were significantly associated with PC-AKI, including age, male, diabetes, CRP, LVEF, excess volumes of CM and preoperative statins therapy." (PMID 34225750, 2021). "It was found that age, prediabetes, diabetes, BMI, hypertension, and CRP were significantly associated with an increased risk of total cancer in young adults." (PMID 34527591, 2021). "Diabetes has been shown to be an inflammatory process associated with elevated levels of interleukin-1, interleukin-6, C-reactive protein, and tumor necrosis factor-α throughout the body." (PMID 34772392, 2021). "Chronic low-grade inflammation has been associated with higher incidence of diabetes through worsening of insulin resistance and it has been shown that diet can effectively influence inflammation as assessed by C-reactive protein in a meta-analysis of RCTs." (PMID 34836416, 2021). "Diabetes is linked to augmented circulating inflammatory biomarkers including C-reactive protein and fibrinogen." (PMID 34831711, 2021).